MTHFD2 (methylenetetrahydrofolate dehydrogenase (NADP+ dependent) 2, methenyltetrahydrofolate cyclohydrolase)
Diseases named in the same sentence as MTHFD2 in open-access papers (continued):
Sharing a sentence is not in itself a finding about the gene and the disease.
renal cell carcinoma (13 papers, 2013 to 2025). "Consequently, MTHFD2 establishes an association between the RNA methylation status in renal cell carcinoma and the metabolic state of tumor cells." (PMID 39759516, 2024). "MTHFD2 has been reported to affect the protein modulation of HIF1α by regulating m6A modification in renal cell carcinoma, which leads to decreased glycolytic capacity of renal tumor cells." (PMID 40280919, 2025). "Methylenetetrahydrofolate dehydrogenase 2 (MTHFD2), a mitochondrial enzyme, is a key enzyme in the one-carbon metabolic pathway; research has found that the expression of MTHFD2 is significantly upregulated in renal cell carcinoma (RCC)." (PMID 40332101, 2025). "In renal cell carcinoma, MTHFD2 promotes the methylation of HIF-2α mRNA through metabolic reprogramming." (PMID 38794278, 2024). "In renal cell carcinoma, MTHFD2 promotes the mRNA methylation of HIF‐2α via metabolic reprogramming." (PMID 34121323, 2021). "In line with our results, MTHFD2 has been shown to co‐express with cell cycle–related proteins, as well as to promote tumour growth in hepatocellular carcinoma and renal cell carcinoma." (PMID 34121323, 2021). "MTHFD2 overexpression not only facilitates cancer cell migration and invasion, but also predicts poor clinical outcomes in hepatocellular carcinoma and renal cell carcinoma." (PMID 34121323, 2021). "Furthermore, MTHFD2 expression was found to be significantly elevated in renal cell carcinoma, with sequencing data indicating that MTHFD2 can promote the translation of HIF-2α, thereby further enhancing aerobic glycolysis." (PMID 39759516, 2024). "Interestingly, MTHFD2 is important for maintaining global N6-methyladenosine (m6A) methylation levels in renal cell carcinoma (RCC)." (PMID 32933024, 2020). "Moreover, although MTHFD2 expression was low in other solid tumors analyzed in this study, high levels of MTHFD2 were detected in metastatic samples derived from colon cancer and renal cell carcinoma patients, indicating that MTHFD2 may promote tumor progression also in other solid tumors." (PMID 23295955, 2013).
lung adenocarcinoma (12 papers, 2018 to 2024). A carcinoma that arises from the lung and is characterized by the presence of malignant glandular epithelial cells. "SHMT2 and methylenetetrahydrofolate dehydrogenase, MTHFD2, key enzymes of the mitochondrial folate cycle, were likewise found to be overexpressed in lung adenocarcinoma and/or associated with poor prognosis." (PMID 38515202, 2024). "We studied the association between MTHFD2 expression levels and the prognosis of lung adenocarcinoma patients." (PMID 30532069, 2019). "Among the lung adenocarcinoma samples, 7% (17 out of 230 patients) showed MTHFD2 alterations (amplification, mutation, or mRNA upregulation)." (PMID 29335598, 2018). "In lung adenocarcinoma, MTHFD2 promoted cell growth and metastasis via AKT/GSK‐3β/β‐catenin signalling." (PMID 37480214, 2023). "Methylenetetrahydrofolate dehydrogenase 2 (MTHFD2) is a key enzyme involved in the m1C cycle, which plays a role in metabolic reprogramming, immune evasion, and disease progression in multiple cancers, including prostate cancer, lung adenocarcinoma, and ESCA." (PMID 38373930, 2024). "In addition, stage I lung adenocarcinoma patients can be stratified into a good prognostic group with low-level MTHFD2 expression and a poor prognostic group with high-level MTHFD2 expression in cancer tissues." (PMID 30532069, 2019). "The expression levels of MTHFD2 were clearly correlated with poor prognosis, advanced stage, as well as undifferentiated grades, and the expression level served as an independent prognostic marker in lung adenocarcinoma." (PMID 30532069, 2019). "However, the specific role and mechanism of MTHFD2 in lung adenocarcinoma (LUAD) still remains unclear." (PMID 34121323, 2021).
bladder cancer (11 papers, 2012 to 2025). "Supporting these observations, elevated expression of MTHFD2 has been previously associated with increased risk of bladder cancer." (PMID 23295955, 2013). "We aim to examine the suitability of MTHFD2 to be a novel biomarker of bladder cancer and whether MTHFD2 is linked to immune infiltration." (PMID 35581573, 2022). "Elevated expression of MTHFD2 has been previously associated with increased risk of bladder cancer." (PMID 23295955, 2013). "In bladder cancer cells, MTHFD2 was shown to promote proliferation and migration by upregulating MYC through the AKT pathway." (PMID 40604332, 2024). "MTHFD2 contributes to tumorigenesis and immune evasion in a variety of cancers, and induces immune escape through upregulation of PD-L1 in pancreatic and bladder cancers." (PMID 38625586, 2024). "Expression of MTHFD2 in bladder cancer tissues correlates with PD‐L1 expression, which was proposed to be mediated by the PI3/AKT and JAK/STAT pathways." (PMID 39540204, 2024). "Western blot analysis was performed to detect MTHFD2 expression in human bladder cancer (BLCA) cells and normal urothelial cell line SV-HUC-1." (PMID 35581573, 2022). "This suggests that MTHFD2 might have promoted the transition from G1 to S phase to regulate cell cycle and consequently contribute to the oncogenesis of bladder cancer." (PMID 35581573, 2022). "Recently, MTHFD2 was found to affect bladder cancer cell growth by activating CDK2." (PMID 35581573, 2022). "Collectively, high MTHFD2 predicts an inflamed TME, a basal-like subtype, and a better response to various therapeutic strategies, especially the ICB therapy, in bladder cancer." (PMID 38130721, 2023). "As expected, the expression of MTHFD2 correlated positively with the expression of PD‐L1 (r = 0.7434, p = 0.001), and phosphorylation of JAK1 (r = 0.7926, p < 0.001) and STAT3 (r = 0.8613, p < 0.001) in bladder cancer tissues." (PMID 37480214, 2023). "In addition, it has been reported that MTHFD2 is present in the nucleus and interacts with cyclin-dependent kinase 2 (CDK2), and plays an important role in bladder cancer through non-metabolic functions." (PMID 40280919, 2025).
leukemia (11 papers, 2019 to 2025). A malignant (clonal) hematologic disorder, involving hematopoietic stem cells and characterized by the presence of primitive or atypical myeloid or lymphoid cells in the bone marrow and the blood. "Our data thus suggests ontogenic differences in the sensitivity of MLL::ENL-driven leukemia to inhibition of pathways under the control of Mthfd2 and Mtap, highlighting potential opportunities for age-tailored therapeutic approaches." (PMID 38555405, 2024). "As cancers often display increased reliance on MTHFD2 function, the findings summarized here emphasize the potential of MTHFD2 targeting in cancer therapy, and indeed, it was shown recently to be a suitable target for inhibition of leukemia growth." (PMID 37949226, 2023). "Lastly, it was reported that loss of MTHFD2 impaired growth and induced differentiation in AML cell lines and primary AML blasts, while it decreased leukaemia burden in human xenograft and MLL-AF9 mouse leukaemia models." (PMID 33707653, 2021). "A recent study reported that the oncogenic transcription factor Myc is involved in the expression of MTHFD2 in leukemia cells and tumor-initiating cells in glioblastoma." (PMID 30532069, 2019). "Furthermore, we showed that MTHFD2, together with other members of the one-carbon pathway, localizes to chromatin in leukemia cells." (PMID 40604332, 2024). "Furthermore, wepresent the first systematic establishment of a cell screening platformfor MTHFD2 inhibitors using a diverse panel of leukemia and solidtumor cell lines." (PMID 39591507, 2024). "Moreover, this study pioneered the establishment ofa comprehensivecell screening platform for MTHFD2 inhibitors using a diverse panelof leukemia and solid tumor cell lines." (PMID 39591507, 2024). "Furthermore, they showed that MTHFD2 suppression decreased leukemia burden and prolonged survival in MLL-AF9 mouse leukemia models and a human xenograft model." (PMID 33652666, 2021). "As MTHFD2 has been validated with small hairpin RNA as a target in AML19, we next validated our inhibitors in a panel of leukemia cell lines, including acute lymphoblastic leukemia (ALL) and AML cells, as well as nontumorigenic LCLs established from healthy donors, LCL-534 and LCL-889." (PMID 35228749, 2022).
glioblastoma (8 papers, 2019 to 2025). The most malignant astrocytic tumor (WHO grade IV). "Another study on glioblastoma multiforme (GBM) proposed a survival-prediction gene signature in which MTHFD2 was one of the protect factors." (PMID 32411609, 2020). "Previous studies have indicated that MTHFD2 can specifically regulate the PERK/ATF4 axis in glioblastoma cells, and the variation in our findings may be attributed to the differences in cell types and experimental conditions." (PMID 39247810, 2024). "To determine if tumor recurrence in glioblastoma patients who have undergone TMZ chemotherapy is associated with an increase in de novo purine synthesis enzyme expression, we performed IHC to determine the expression of metabolic enzymes DHFR, MTHFD2, and PAICS in ID-1-high patients." (PMID 39455562, 2024). "Previous studies have shown that c-Myc is a transcription factor for MTHFD2 in AML and glioblastoma." (PMID 40280919, 2025). "Within this environment, MTHFD2 attracted considerable interest for the first time, and indeed, a large number of studies have confirmed the transcriptional upregulation of MTHFD2 across cancer types: breast, AML, glioblastoma, and kidney cancer, among others." (PMID 41303507, 2025).
hepatocellular carcinoma (8 papers, 2020 to 2026). A malignant tumor that arises from hepatocytes. "Increased MTHFD2 levels are also associated with the migration, invasion, and poor clinical prognosis of breast cancer, NSCLC, RCC, hepatocellular carcinoma (HCC), squamous cell carcinoma (SCC), and ovarian cancer." (PMID 40863132, 2025). "Conversely, MTHFD2 can also be activated by β-catenin in hepatocellular carcinoma, where MTHFD2 was found to mediate the oncogenic function of nucleoside diphosphate kinase 7 (NME7), which induces the Wnt/β-catenin pathway that activates MTHFD2 expression." (PMID 40604332, 2024). "MTHFD2 is relatively lowly expressed in normal tissues and is upregulated in different cancers, including breast, colorectal, and hepatocellular cancers, where it plays a key role in remodeling the folate metabolism of tumor cells." (PMID 35888776, 2022). "Genes involved in the biosynthesis of asparagine (Asns) and serine (Phgdh) and in folate metabolism (Mthfd1l and Mthfd2) were also elevated in Nod2−/− DMBA + HFD mice and are associated with the development of hepatocellular carcinoma." (PMID 33239685, 2020).
ovarian carcinoma (8 papers, 2021 to 2023). A malignant neoplasm originating from the surface ovarian epithelium. "This study found that MTHFD2 is highly expressed in ovarian cancer, as well as an indispensable risk factor for poor prognosis in patients with ovarian cancer." (PMID 37628752, 2023). "We found that the main type of mutation of MTHFD2 in ovarian cancer was missense substitutions mainly occurred in THF_DHG_CYH domain." (PMID 35135596, 2022). "As determined using cBioPortal, the MTHFD2 mutation frequency (0.34%) in patients with ovarian cancer." (PMID 35135596, 2022). "In summary, through our study found that MTHFD2 is highly expressed in ovarian cancer, as well as an indispensable risk factor for poor prognosis in patients with ovarian cancer." (PMID 35135596, 2022). "Furthermore, MTHFD2 mutations in ovarian cancer samples were A > C (2.68%), A > G (4.46%), A > T (0.00%), C > A (13.39%), C > T (22.32), C > G (8.04), G > A (21.43%), G > C (7.14%), G > T (8.04), T > A (8.04%), T > C (5.36%), T > G (2.68%)." (PMID 35135596, 2022). "Our results demonstrated that MTHFD2 expression in ovarian cancer was up-regulated and associated with poor prognosis in ovarian cancer patients, which may play a role in malignant transformation mainly through MOB1A signaling pathway." (PMID 35135596, 2022). "Therefore, the current study devoted to exploring the potential value of MTHFD2 for the diagnostic and prognostic of ovarian cancer, as well as its underlying regulation mechanism." (PMID 35135596, 2022). "Besides, we used ovarian cancer cell lines to analyze the regulatory mechanism underlying the effect of highly expressed MTHFD2 on ovarian cancer." (PMID 35135596, 2022). "There is increasing evidence to suggest that MTHFD2 expression is relevant to tumor progression in many cancers, including head and neck cancer, lung cancer, kidney cancer, and ovarian cancer." (PMID 36726381, 2023). "MTHFD2 transcripts were elevated significantly in ovarian cancer samples compared to normal tissue (P < 0.05)." (PMID 35135596, 2022). "The prognostic value of MTHFD2 expression was validated by our own ovarian cancer samples using RT-qPCR." (PMID 35135596, 2022). "These experiments preliminarily demonstrate that MTHFD2 exerted its effects on the malignant behaviors of ovarian cancer cells through the MOB1A signaling pathway." (PMID 35135596, 2022). "According to GEPIA database, MTHFD2 expression was significantly increased in ovarian cancer tissues compared with adjacent normal controls." (PMID 35135596, 2022). "Then, CCK-8 assay demonstrated that MTHFD2 knock-down significantly weakened the ability of proliferation of ovarian cancer." (PMID 35135596, 2022). "We adopt bioinformatics methods to observe the expression ad prognostic value of MTHFD2 in ovarian cancer." (PMID 35135596, 2022). "In the present study, to determine the role and functional network of MTHFD2 in the ovarian cancer, we performed bioinformatics analyses to analyze the extensive gene expression profiling with pre-defined parameters in ovarian cancer and normal samples." (PMID 35135596, 2022). "The results showed that MTHFD2 exrpession is only significantly positively correlated with neutrophils (r = 0.21, p = 8.51 × 10− 4) in ovarian cancer." (PMID 35135596, 2022). "Subsequently, we further identified the function of MTHFD2 in growth and metastasis of ovarian cancer cells through knockdown the expression of MTHFD2 using siRNA technology." (PMID 35135596, 2022). "MTHFD2 functioned as a critical protumorigenic factor involved in ovarian cancer progression via STAT3 signaling pathway." (PMID 34231329, 2021). "MTHFD2 depletion inhibits cell growth and metastasis and induces G2/M arrest and apoptosis in ovarian cancer cell lines." (PMID 34231329, 2021). "Methylenetetrahydrofolate dehydrogenase 2 (MTHFD2) is overexpressed in ovarian cancer tissues and cell lines." (PMID 34231329, 2021).
ovarian carcinoma (continued). "Our results demonstrated that the expression of MTHFD2 was detected in most ovarian cancer cell lines at mRNA and protein levels." (PMID 34231329, 2021). "Knockdown of MTHFD2 in ovarian cancer cells reduced the proliferation, induced the G2/M cell cycle arrest and cell apoptosis." (PMID 34231329, 2021). "In the current study, MTHFD2 was significantly upregulated in ovarian serous carcinoma tissues and ovarian cancer cell lines." (PMID 34231329, 2021). "Next, to further investigate the mechanism of the inhibitory effect on ovarian cancer cell growth, we postulated that MTHFD2 regulates ovarian cancer cell cycle progression." (PMID 34231329, 2021). "We further adopt our own results validated that that MTHFD2 mRNA expression may be an independent prognostic biomarker in ovarian cancer patients." (PMID 35135596, 2022). "To evaluate whether MTHFD2 expression level has predictive significance for ovarian carcinoma prognosis, we detected the expression of MTHFD2 mRNA and its relationship with prognosis." (PMID 35135596, 2022). "However, the function of MTHFD2 in the development of ovarian cancer and its potential molecular mechanisms is still unclear." (PMID 35135596, 2022). "Our experiments confirmed that MTHFD2 might be a potential factor promoting the proliferation, migration, and invasion of ovarian cancer." (PMID 35135596, 2022). "Furthermore, we detected our own clinical samples found that the overexpression of MTHFD2 mRNA and worse probabilities of survival in ovarian cancer." (PMID 35135596, 2022). "However, the prognostic value and signal transduction of MTHFD2 expression in ovarian cancer is still ambiguous." (PMID 35135596, 2022). "Taken together, our results suggest that targeting MTHFD2 maybe served as a novel approach for ovarian cancer treatment." (PMID 34231329, 2021). "Our findings demonstrated that MTHFD2 is upregulated in ovarian cancer tissues and cell lines." (PMID 34231329, 2021). "The expression of MTHFD2 was related to ovarian cancer proliferation." (PMID 34231329, 2021). "Therefore, we conducted qPCR and western blot analysis, which indicated that most ovarian cancer cell lines exhibited high MTHFD2 expression." (PMID 34231329, 2021). "We found that MTHFD2 is highly expressed in both ovarian cancer tissues and cell lines." (PMID 34231329, 2021). "Taken together, our results indicate an inhibitory effect of MTHFD2 knockdown on tumor development and suggest that targeting MTHFD2 maybe served as a novel approach for effective treatment of ovarian cancer." (PMID 34231329, 2021). "Moreover, inhibitory regulators such as p‐wee1, p21waf1/cip1, and p27kip1 were increased in the MTHFD2 silencing ovarian cancer cells." (PMID 34231329, 2021). "According to our bioinformatic analysis and the IHC results of TMA, MTHFD2 is overexpressed in ovarian serous carcinoma and lymphatic metastasis which indicates that MTHFD2 may play an important role in the progression of ovarian cancer." (PMID 34231329, 2021). "Besides, the expression of MTHFD2 in ovarian cancer was detected by immunohistochemical analysis using commercially available tissue microarray (TMA)." (PMID 34231329, 2021). "However, the exact role of MTHFD2 in ovarian cancer and its underlying regulatory mechanism have not been elucidated." (PMID 35135596, 2022). "Finally, the expression of MOB1A was inhibited by MTHFD2 in ovarian cancer cells." (PMID 35135596, 2022). "All the results above suggest that MTHFD2 may contribute to ovarian cancer development." (PMID 34231329, 2021). "By mining co-expression and correlation analysis data, we determined that MTHFD2 and MOB1A were both upregulated in ovarian cancer." (PMID 35135596, 2022). "Consistently, after knock down MTHFD2, we found that the expression of MOB1A was significantly decreased in ovarian cancer cell lines." (PMID 35135596, 2022).
ovarian carcinoma (continued). "We also found that that MTHFD2 has a role in malignancy mainly through the MOB1A signaling, which is a potential target for treating ovarian cancer." (PMID 35135596, 2022). "MTHFD2, as a NAD + -dependent enzyme, accelerated tumor progression by up-regulating MBO1A, suggesting that this protein may be an independent prognostic factor and a potential therapeutic target for future ovarian cancer treatments." (PMID 35135596, 2022). "However, the role of MTHFD2 in ovarian cancer has not been determined." (PMID 34231329, 2021).
prostate carcinoma (8 papers, 2021 to 2025). A carcinoma that arises from epithelial cells of the prostate gland. "ATF4 and c-MYC promote tumor cell growth by synergistically regulating MTHFD2, and MTHFD2 is identified as a biomarker or therapeutic target for prostate cancer." (PMID 38336749, 2024). "Proliferation and migration of tumor cells in colon cancer are facilitated by PPFIA4’s ability to increase tumor glycolysis; PPFIA4 also increases mitochondrial metabolism via MTHFD2 in desmoplastic-resistant prostate cancer." (PMID 35924146, 2022).